CD4 (CD4 molecule)
Diseases named in the same sentence as CD4 in open-access papers (continued):
Sharing a sentence is not in itself a finding about the gene and the disease.
viral infection (continued). "These aspects highlight potential mechanistic failures that delay the maturation of CD4+ T cell activation and function, facilitating viral infection in younger children." (PMID 39200373, 2024). "While recent studies characterizing CD4+ T cell heterogeneity during acute viral infection identified the presence of precursor TCM (pTCM) at a single time point of the analysis, such a snapshot approach precluded assessment of their developmental dynamics." (PMID 39321257, 2024). "Viral infection primarily targets CD4+ T-cells and macrophages when the number of CD4 T-cells drops by 200 cells/μL; people living with HIV (PLHIV) then become susceptible to opportunistic infections, including SARS-CoV-2." (PMID 39335628, 2024). "CD4+/CD25+FoxP3+ regulatory T cells (Tregs) play an important role in the immune response to viral infections and especially in the balance between immunity and tolerance." (PMID 38979428, 2024). "Although the relationship between ferroptosis of CD4+ T cells and anti-tumor effect is not clear so far, studies have reported that ferroptotic stress is harmful for CD4+ T cells’ function in defending against virus infection." (PMID 39134539, 2024). "Predominant multifunctional CD4+ T cells together with enhanced IFN-γ+ CD8+ T cells specific to SARS-CoV-2 antigens after viral infection have been reported previously." (PMID 38416834, 2024). "Although most adoptive transfer studies with memory B and T cells are focused on viral infections, some studies evaluate the protective effect of CD4+ T cells in bacterial infections." (PMID 39408879, 2024). "Our findings suggest that CD8+ T cells from the MLN and CD4+ T cells from various peripheral lymph nodes play a compensatory role in the immune response against viral infections in the mice with splenectomy." (PMID 38770891, 2024). "CD4+ T cells play a key role in the coordination of the immune system response to acute and chronic viral infection by activating multiple cells of the innate immune system, B cells, CD8+ T cells and non-immune cells." (PMID 39274228, 2024). "The severity of anemia, leukopenia/neutropenia, and thrombocytopenia is influenced by the low levels of CD4+ lymphocytes, viral load, and the stage of viral infection." (PMID 39330902, 2024). "To assess the role of Itga4 deficiency in CD4 T cells during acute viral infection, we adoptively transferred SMARTA CD4 T cells, either transfected with crItga4 C+D or control crCd8, into WT B6 recipient mice." (PMID 39720725, 2024). "The PEP-619WW DC and PEP-619WW CD4 T cell have an additive effect on anti-viral T cell function, which in turn controls the chronic viral infection." (PMID 38512979, 2024). "Rapamycin has also been demonstrated to affect B cell and CD4+ T cell responses in a mouse model of viral infection." (PMID 38791040, 2024). "Chemoattraction to follicles via direct secretion of CXCL13 by TFH cells or indirect promotion of CXCL13 secretion from mesenchymal cells by IL-17+ CD4+ T cells are known components of T cell help to B cells, including in the lung after viral infection." (PMID 38715601, 2024). "In P2–P8 (PWH on suppressive ART), 5 host genes were significantly upregulated in HIV-1 RNA–producing CSF CD4 TCM, including the nucleoporin gene NUP210, previously associated with viral infection in vitro." (PMID 38587074, 2024). "Previous studies have demonstrated that Se supplement attenuated viral infection and/or cancer growth by enhancing the proliferation and activation of CD4+ T cells, CD8+ T cells, natural killer cells, and/or APCs." (PMID 39197316, 2024). "CD4+ T cells, known as helper T cells, recognize viral infections and activate the immune system, while CD8+ T cells, referred to as cytotoxic T cells, identify and eliminate infected cells." (PMID 39449801, 2024). "For several years now, the role of cytotoxic CD4 T cells in the control of viral infections and in tumor immunity has been recognized." (PMID 38273012, 2024).
viral infection (continued). "involvement of exosomes) between the HIV-infected CD4+ thymocytes and this virus infection-resistant CD34+ HSPCs through miRNA transfer from the CD4+ to CD34+ cells requires continued investigation." (PMID 38721526, 2024). "PD-1 was widely recognized as an inhibitory marker on CD8 and CD4 T cells in chronic viral infections in humans, such as chronic HIV, HBV, and HCV infections." (PMID 38957797, 2024). "They participate in antigen presentation and activate the adaptive immune response cells during viral infections, including CD4+ and CD8+ T lymphocytes." (PMID 39764446, 2024). "IL-6 is critical for activation of CD4+ T-cells and Th2 responses during viral infections in humans." (PMID 39541407, 2024). "To measure ADCP of HIV-infected cells, we established a CD4+ T cell line with an enhanced green fluorescent protein (eGFP) reporter gene that is induced by virus infection." (PMID 39466835, 2024). "The control of viral infection in NIFs is mediated primarily by CD4 and CD8 T cells in an IFNγ-dependent manner." (PMID 39134803, 2024). "Viral infections therefore induce a CD4+ memory T cell population that can mount a rapid antigen-independent IFN-γ response." (PMID 38838013, 2024). "Our data show that γδ T cells, after viral infection, exhibit a gene expression pattern distinct from CD4+ and CD8+ T-cells, but with an upregulated gene pattern more akin to universally activated genes across all cell subgroups." (PMID 38743760, 2024). "In response to viral infection, CD4+ T cells primarily differentiate into Th1 cells and secrete significant quantities of IFNγ." (PMID 38770891, 2024). "Here, we show that memory CD4+ T cells generated in response to a viral infection are also capable of mounting an early IFN-γ response in unrelated heterologous challenges." (PMID 38838013, 2024). "CD4+ T cells can differentiate into Th1 and Th2 cells, which have critical roles in the immune response, including clearance of viral infections and regulating immunoglobulin class switching." (PMID 39340038, 2024). "In the chronic stage of the viral infection, the number of CD4+ lymphocytes declines steadily while the virus keeps replicating, although at a lower level than in the acute phase." (PMID 38667150, 2024). "This study used a well‐established splenectomy model to examine the phenotype and function of CD8+ and CD4+ T cells in various peripheral lymph nodes during both homeostasis and viral infection scenarios." (PMID 38770891, 2024). "We revealed the response status of CD8+ and CD4+ T cells in various lymph nodes during both homeostasis and viral infection after splenectomy." (PMID 38770891, 2024). "This study aimed to investigate the characteristics and function of CD8+ and CD4+ T cells in different peripheral lymph nodes during viral infection using a well‐established splenectomy model." (PMID 38770891, 2024). "The severity of these disorders is influenced by the low levels of CD4+ lymphocytes, viral load, and the stage of viral infection." (PMID 39330902, 2024). "The single HIV infection scRNAseq study evaluated viral infection and latency in primary CD4+ T cells isolated from two healthy human donors and infected ex vivo using the recombinant pNL4-3-Δ6-drEGFP HIV strain." (PMID 38478395, 2024). "We have shown that HLA-DRB1*0101 Ifnar1−/− mice, mount an antigen-specific CD4+ T cell response against SARS-CoV-2 after DNA vaccination or viral infection, and a CD4+ T cell response to OC43 that cross-reacts with SARS-CoV-2." (PMID 38278784, 2024). "CD4+ T cells with cytotoxic properties have also been described in the setting of chronic immune stimulation from viral infection, autoimmunity, or cancer." (PMID 37191720, 2023). "While the earliest studies identified cytotoxic CD4 T cells in viral infection models, they have also been recently identified in anti-tumor immune responses and in chronic inflammatory responses during auto-immune/auto-inflammatory diseases." (PMID 37654482, 2023).
viral infection (continued). "Although CD4+ CTL have been recognized for decades in viral infections, they only recently attracted attention as direct anti-tumor effectors in solid cancers." (PMID 37965314, 2023). "In antitumor vaccination and virus infection models, the transcriptional differences in CTLs with the help of CD4+ T cells has been identified through RNA‐sequencing." (PMID 37829505, 2023). "Therefore, viral infection of the brain, including in immunocompetent cases with near-normal levels of CD4 blood lymphocytes, could be associated with an early disruption in microglia-dependent neuronal support functions, contributing to cognitive and neurological deficits in people living with HIV." (PMID 37947981, 2023). "In many viral infections, CD4+ and CD8+ T cells are key cellular subsets for the control and clearance of an acute infection." (PMID 37398654, 2023). "CS-induced lymphopenia, mainly of the CD4+ subset with an altered CD4/CD8 ratio, makes patients more susceptible to viral infections (." (PMID 37338722, 2023). "TCF-1 has been shown to play a critical role in CD4 T cell exhaustion and activation in responding to viral infections." (PMID 36901757, 2023). "Past studies have shown that CD4+ T cells are necessary for the protection of mice against lethal viral infection." (PMID 36992167, 2023). "CD4cyt are expanded in patients with heterozygous CTLA4 mutations, and the cytotoxicity of CD4+ T cells is increased in cancer patients after ICI therapy and in a mouse model of acute viral infection after CTLA4 blockade." (PMID 37161048, 2023). "Another study on infant acute lung injury during viral infection showed that there is a correlation between a reduced CD4+ to CD8+ ratio and lung damage and so brings credence to the clinical trials involving MSCs as a therapeutic for COVID-19 infections." (PMID 37259300, 2023). "Metformin demonstrates prominent impacts on the differentiation and activation of CD4+ and CD+8 T cells in various disease states, such as virus infection, autoimmune diseases, aging, and cancers." (PMID 36614197, 2023). "Viral infections and intracellular bacterial infections can provoke strong CD4 and CD8 T cell responses." (PMID 36839601, 2023). "These cytotoxic CD4+ T cells have been shown to limit viral infections in an MHC II-dependent mechanism." (PMID 38274806, 2023). "CCR5 is expressed on CD4+ T cells, particularly Th1 lymphocytes, and is involved in viral infections and tumor growth." (PMID 37380639, 2023). "CD2AP expressed on the surface of CD4+ T cells regulates follicular helper T cell differentiation and enhances antibody responses during viral infection." (PMID 37949890, 2023). "The other possibility is a sequential virus infection, i.e., each contact of CD4+ T cells with a cell-free virus results in the transmission of one viral genome to the target cell." (PMID 37476291, 2023). "In agreement with the findings from the mouse study, data from human patients has shown that Cytomegalovirus (CMV), a chronic viral infection, strongly expands cytotoxic CD4 T cells." (PMID 37654482, 2023). "Our results demonstrate that SEACells can capture biologically meaningful CD4+ T cell subsets, highlighting the transition from the spectrum of active to quiescent differentiated states during a multi-day viral infection." (PMID 36973557, 2023). "T cells play a central role in various viral infections, with CD4 + T cells mediating antibody production by B cells and coordinating the responses of other immune cell types, as well as directly initiating the immune response to infectious agents." (PMID 37964304, 2023). "Together, these cells are the main constituents of T cell-mediated responses since CD8 cells are known to fight viral infections and cancer cells while CD4 cells support CD8 cell function." (PMID 37238610, 2023). "Under pathologic conditions, CD4 CTLs hasten the development of autoimmune disease or viral infection by enhancing cytotoxicity." (PMID 36737819, 2023).
viral infection (continued). "CD4+-T-cells are a central link in the adaptive immune system with implications for opportunistic and viral infections, previously demonstrated for MM patients receiving traditional chemotherapy and bortezomib." (PMID 37152008, 2023). "CD4+ CTLs play a protective role against several chronic and acute viral infections, such as HIV, Epstein-Barr virus, and Dengue virus." (PMID 38077321, 2023). "CD4+ T cells differentiate into multiple effector functions, including Th1, Th2, Treg, and Tfh cell types, which impact viral infections." (PMID 38274806, 2023). "Cytotoxic CD4+ T cells were described to compensate for the CD8+ killing capacity in different viral infections under certain circumstances, especially in chronic infections when CD8+ T cell exhaustion develops." (PMID 37883584, 2023). "The importance of CD4 T cell persistence has been shown in autoimmunity, cancer, viral infection, and several cardiovascular diseases." (PMID 36901757, 2023). "While VLPs have been shown to be effective inducers of CD4+ helper T cells and antibodies, transduction with viral vectors resembles natural viral infections and elicits CTL responses by presenting antigens in an inflammatory context." (PMID 37112906, 2023). "Upon viral infection, antigen presenting cells carry viral antigens to the draining lymph node to activate naive CD4 and CD8 T-cells." (PMID 38150441, 2023). "During chronic viral infection, Th1 cells progressively lose, while virus‐specific CD4+ T cells tend to polarize into Tfh cells." (PMID 37829505, 2023). "Similar to CD8+ T cells, CD4+ T cells become exhausted due to continued antigen stimulation during chronic viral infection." (PMID 37829505, 2023). "Studies employing the non‐fatal rabies virus strain, CVS‐F3, have shown that clearance of viral infection is dependent on regulation of BBB permeability by effector CD4 T cells that migrate to the CNS." (PMID 37767784, 2023). "In contrast to viral infections CD4+ CTL attracted attention as direct anti-tumor effectors in solid cancers only recently." (PMID 37965314, 2023). "Our assessment of pediatric inflammatory conditions demonstrated a greater expansion of CD38+HLA-DR+ CD4+ T cells and CD8+ T cells in SD-associated MAS and MAS secondary to other causes than in MIS-C, Kawasaki Disease, and common viral infections." (PMID 37751296, 2023). "CD4+ T cells are unessential for controlling acute viral infections, while they play an important role in the elimination of chronic viral infection due to their roles of helping CD8+ T cells priming and sustaining their function." (PMID 37829505, 2023). "In a pre-existing Mtb infection, specifically within the granuloma, HIV encounters a highly permissive CD4+ T lymphocyte population expressing the membrane receptors required for viral infection (CD4, CCR5, or CXCR4)." (PMID 37110276, 2023). "Increase in CD4+ T cell expansion and survival can be observed in acute viral infections when endogenous IFNβ is released." (PMID 37325639, 2023). "CD25+Foxp3+CD4+ regulatory T cells (Tregs) have an important inhibitory effect during viral infection." (PMID 37773701, 2023). "Published data have shown that CXCR3 expression is directly linked to T-bet expression in EM cells during viral infections, and that TCF-1 controls the chemokine receptor expression in CD4 T cells and their trafficking to GvHD target organs." (PMID 36901757, 2023). "Despite this, the IL-33/ST2 signaling pathway has well-defined roles in T cell activation during viral infection, with CD8+, CD4+, and Treg cells implicated." (PMID 37983247, 2023). "The CD4 T cell phenotype has been extensively studied in response to viral infections, cancer, and GvHD." (PMID 36901757, 2023). "Rong and collaborators have used models to study the infection dynamics of CD4+ T cells and macrophages via cell-free virus infection and cell-to-cell viral transmission." (PMID 37476291, 2023).
viral infection (continued). "CD4 T cell activation, signaling proliferation, and Th1/Th2/Th17 differentiation are central to both CD4 T cell function and CD4 T cell-mediated diseases, including CD4 T cell responses to viral infection, autoimmunity, cancer, and aging." (PMID 36901757, 2023). "Specifically, studies have reported that activated NK cells after vaccination or viral infection can eliminate CD4 and CD8 T cells." (PMID 37711632, 2023). "On the other hand, the CD4+ subset plays a critical role in virus infection through the activation and differentiation of virus-specific B cells." (PMID 36851216, 2023). "Most effector CD4/CD8 T cells die after viral infection, but only a small number of memory T cells persist in the long term at the infection site." (PMID 37507413, 2023). "CD4+ T cells are vital cells in the human immune system and play an important role in alleviating bacterial and viral infections and in tumor immunity." (PMID 37360336, 2023). "As CD4+ CTL have been intensively studied in the context of viral infections, this led to the idea of exploiting those cells also in therapy on solid cancers." (PMID 37965314, 2023). "Important components of the adaptive immune system that are crucial in preventing the majority of viral infections are B cells, CD4 T cells, and CD8 T cells." (PMID 37426635, 2023). "In viral infections, CD4+ CTL often kill via the Fas/FasL pathway, but they can also facilitate the exocytosis pathway of killing." (PMID 37965314, 2023). "Cytotoxic CD4+ T cells are well described in mice and humans in the context of viral infections, autoimmunity, and cancer." (PMID 36911660, 2023). "This alternative is especially attractive as both CD103+ DCs and CD11bhi DCs are critical mediators of CD8+ and CD4+ T cell responses during viral infections." (PMID 36845082, 2023). "Nonetheless, exhausted CD4+ T cells received less attention and was less known about their mechanism of action during chronic viral infection." (PMID 37829505, 2023). "CD4 T cells with cytotoxic function were first described in the setting of viral infections and autoimmunity, and more recently in cancer and gut dysbiosis." (PMID 37654482, 2023). "Given that type I IFN-stimulated genes remain elevated for several weeks following chronic viral infection, this finding suggests that all subsets of CD4+ T cells are likely to experience some degree of type I IFN signaling during persistent viral infection." (PMID 36255051, 2022). "MuLV/Friend virus infection led to a rapid and progressive depletion of CD4+ T cells as expected, and a significant increase of both CD8+ T and NK cells in the spleen of both wild type (WT) and Sash mice." (PMID 35197951, 2022). "Specifically, PWH have diminished or less durable responses to hepatitis B and yellow fever vaccination, and people with low CD4 cell counts have diminished antibody titers to pneumococcus, influenza, diphtheria, tetanus, and poliomyelitis." (PMID 36679862, 2022). "Different studies have established that IL-12 produced by monocytes induces IFN-γ production from T cells and also skews the naive CD4+ T cells toward the Th1 phenotype, which helps in eliminating viral infection." (PMID 36445121, 2022). "Correlations between increased T-bet expression and decreased respiratory CD4 TRM formation following viral infection have also been seen in clinical studies." (PMID 36358898, 2022). "Generally, CD4+ TRM cells in viral infection and tumors mainly secreted IFN-γ, while CD4+ TRM cells induced by bacterial or fungal infection mainly expressed IL-17A." (PMID 36471700, 2022). "In viral infections, such as lymphocytic choriomeningitis virus and West Nile virus (WNV) encephalitis, CXCR3 deficiency can affect numbers of CNS-infiltrating CD4+ and CD8+ T cells." (PMID 36704563, 2022). "CD4/CD8 ratio is a marker of persistent inflammation and immunosenescence caused by viral infections." (PMID 36713432, 2022).